KCNH8 (potassium voltage-gated channel subfamily H member 8)
Description:
Pore-forming (alpha) subunit of a voltage-gated delayed rectifier potassium channel that mediates outward-rectifying potassium currents. Elicits a slowly activating, non-inactivating and slowly deactivation outwards potassium current at depolarizating voltages from -30 mV to +50mV. Shows no obvious change in the activation rate from different holding potentials. Activation is strongly dependent on the pH of the external solution (By similarity).
Synonyms: hElk-1; ELK3; Kv12.1; ELK; ELK1
Tractability: Small molecule: an approved drug acts on it; it belongs to a druggable protein family. Antibody: its Gene Ontology location is reachable by antibodies, with high confidence; UniProt predicts a signal peptide or a membrane-spanning region; the Human Protein Atlas places it where antibodies can reach. PROTAC: ubiquitination databases record sites on it.
Gene: Protein-coding gene on chromosome 3 (19,148,102 to 19,535,642, forward strand). Ensembl gene ENSG00000183960.
Subcellular location: Membrane
Subcellular location (Human Protein Atlas): Plasma membrane
Pathways (Reactome):
Neuronal System: Voltage gated Potassium channels
Gene Ontology:
Molecular function: delayed rectifier potassium channel activity; voltage-gated potassium channel activity; monoatomic ion channel activity
Biological process: potassium ion transport; potassium ion transmembrane transport; regulation of membrane potential; monoatomic ion transport; transmembrane transport
Cellular component: plasma membrane; membrane
Genetic constraint (gnomAD): Loss-of-function variants: 65 observed, 98.64 expected, observed/expected ratio (o/e) 0.66, 90% interval 0.54 to 0.81. The upper end of that interval is the gene's LOEUF score, 0.81, which puts it in group 3 of 6, group 1 being the genes least tolerant of losing a copy. Missense variants: 1,142 observed, 1,319 expected, observed/expected ratio (o/e) 0.87, 90% interval 0.82 to 0.91. Synonymous variants: 466 observed, 490.22 expected, observed/expected ratio (o/e) 0.95, 90% interval 0.88 to 1.03.
Homologues: Orthologues: chimpanzee KCNH8 (99% identical), macaque KCNH8 (99% identical), dog KCNH8 (96% identical), pig KCNH8 (95% identical), rabbit KCNH8 (95% identical), guinea pig KCNH8 (94% identical), mouse Kcnh8 (92% identical), rat Kcnh8 (92% identical), tropical clawed frog kcnh8 (75% identical), zebrafish kcnh8 (58% identical), Drosophila melanogaster Elk (44% identical), Caenorhabditis elegans unc-103 (23% identical), and 9 more. Paralogues in human: KCNH4 (52% identical), KCNH3 (48% identical), KCNH2 (33% identical), KCNH7 (33% identical), KCNH6 (30% identical), KCNH1 (29% identical), KCNH5 (28% identical), HCN4 (16% identical), HCN1 (15% identical), HCN2 (15% identical), CNGB1 (13% identical), HCN3 (13% identical), and 5 more.
Diseases named in the same sentence as KCNH8 in open-access papers:
KCNH8 is named in the same sentence as 14 diseases in open-access papers, as found by Europe PMC text mining. Sharing a sentence is not in itself a finding about the gene and the disease. The quoted sentences say what the papers report.
schizophrenia (2 papers, 2020 to 2022). A major psychotic disorder characterized by abnormalities in the perception or expression of reality. "KCNH8 was identified in the context of the neuropsychiatric 15q13.3 microdeletion which is associated with several neuropsychiatric disorders including autism, schizophrenia, and attention deficit hyperactivity disorder." (PMID 33004014, 2020).
autoimmune disease (1 paper, 2019). A disorder resulting from loss of function or tissue destruction of an organ or multiple organs, arising from humoral or cellular immune responses of the individual to their own tissue constituents. "KCNH8 was almost exclusively expressed in B cells and KCNH8 region was associated with susceptibility to autoimmune diseases, including Crohn’s disease and psoriasis." (PMID 31443559, 2019).
lung carcinoma (1 paper, 2025). "Lung cancer studies included E3 (KCNK1), E8 (KCNK1, KCNN4), E12 (KCNH8, KCNMB2), E23 (KCNU1), E30 (KCNQ5-IT1), E35 (KCNK1), E43 (KCNK6), E49 (KCNN4), 2), E54 (KCNJ13), E63 (KCNK12), and E67 (KCNMB2)." (PMID 40867621, 2025).
prostate carcinoma (1 paper, 2021). A carcinoma that arises from epithelial cells of the prostate gland. "In prostate cancer, KCNH8 was identified as a novel outlier gene with potential rearrangement and confirmed the association with primary and metastatic prostate samples." (PMID 34056873, 2021).
cancer (5 papers, 2009 to 2023). A tumor composed of atypical neoplastic, often pleomorphic cells that invade other tissues. "Here we showed that including FABP5 and KCNH8 as prognostic biomarkers improves aggressive cancer detection." (PMID 22811706, 2012). "Several genes that encode these proteins were upregulated in the CD26+ cancer cells: AGR2, BCMP11, CEACAM5/CD66e, CRISP3, KCNG3, KCNH8, LOX and NEO1." (PMID 20021671, 2009).
tumor (4 papers, 2015 to 2024). "Potassium voltage–gated channel subfamily H member 8 (KCNH8) is a member of ELK (EAG-like K+) of the ether-a`-go-go family (KCNH) channels that have been implicated in neuronal excitability, repolarization of cardiac action potential, cell differentiation, and tumor proliferation." (PMID 39156922, 2024). "Respectively, the expression of CDO1, CELF2, ITPRIPL1, KCNH8, RIC3, USP44 and ZSCAN23 was significantly lower in tumor tissues, whereas the expression of PTK6 and RAB25 was significantly higher in tumor tissues." (PMID 34056873, 2021).
KCNH8 also shares sentences with these, for which no sentence is quoted: attention deficit-hyperactivity disorder (1 paper); autism (1); Crohn disease (1); eczema (1); epilepsy (1); psoriasis (1); thrombosis (1); type 2 diabetic (1).